PTPN2 (protein tyrosine phosphatase non-receptor type 2)
Description:
Non-receptor type tyrosine-specific phosphatase that dephosphorylates receptor protein tyrosine kinases including INSR, EGFR, CSF1R, PDGFR. Also dephosphorylates non-receptor protein tyrosine kinases like JAK1, JAK2, JAK3, Src family kinases, STAT1, STAT3 and STAT6 either in the nucleus or the cytoplasm. Negatively regulates numerous signaling pathways and biological processes like hematopoiesis, inflammatory response, cell proliferation and differentiation, and glucose homeostasis. Plays a multifaceted and important role in the development of the immune system. Functions in T-cell receptor signaling through dephosphorylation of FYN and LCK to control T-cells differentiation and activation. Dephosphorylates CSF1R, negatively regulating its downstream signaling and macrophage differentiation. Negatively regulates cytokine (IL2/interleukin-2 and interferon)-mediated signaling through dephosphorylation of the cytoplasmic kinases JAK1, JAK3 and their substrate STAT1, that propagate signaling downstream of the cytokine receptors. Also regulates the IL6/interleukin-6 and IL4/interleukin-4 cytokine signaling through dephosphorylation of STAT3 and STAT6 respectively. In addition to the immune system, it is involved in anchorage-dependent, negative regulation of EGF-stimulated cell growth. Activated by the integrin ITGA1/ITGB1, it dephosphorylates EGFR and negatively regulates EGF signaling. Dephosphorylates PDGFRB and negatively regulates platelet-derived growth factor receptor-beta signaling pathway and therefore cell proliferation. Negatively regulates tumor necrosis factor-mediated signaling downstream via MAPK through SRC dephosphorylation. May also regulate the hepatocyte growth factor receptor signaling pathway through dephosphorylation of the hepatocyte growth factor receptor MET. Also plays an important role in glucose homeostasis. For instance, negatively regulates the insulin receptor signaling pathway through the dephosphorylation of INSR and control gluconeogenesis and liver glucose production through negative regulation of the IL6 signaling pathways. May also bind DNA.
Synonyms: TCPTP; PTPT; TCELLPTP; TC-PTP; TC45; TC48; PTN2
Tractability: Small molecule: a structure with a bound ligand is known; a high-quality ligand is known; it belongs to a druggable protein family. Antibody: its Gene Ontology location is reachable by antibodies, with high confidence; UniProt places it where antibodies can reach, with medium confidence. PROTAC: ubiquitination databases record sites on it; its protein half-life has been measured; a small molecule that binds it is known.
Target class: Tyrosine protein phosphatase; Enzyme; Phosphatase; Protein Phosphatase
Chemical probes: ABBV-CLS-484 (high quality)
Gene: Protein-coding gene on chromosome 18 (12,785,478 to 12,929,643, reverse strand). Ensembl gene ENSG00000175354.
Subcellular location: Endoplasmic reticulum (Isoform 1); Endoplasmic reticulum-Golgi intermediate compartment; Nucleus (Isoform 2); Cytoplasm; Cell membrane
Subcellular location (Human Protein Atlas): Nucleoplasm; Cytosol
Pathways (Reactome):
Immune System: Interleukin-37 signaling; PKR-mediated signaling; Regulation of IFNG signaling
Signal Transduction: Negative regulation of MET activity
Gene Ontology:
Molecular function: integrin binding; protein binding; protein kinase binding; protein tyrosine phosphatase activity; receptor tyrosine kinase binding; syntaxin binding; non-membrane spanning protein tyrosine phosphatase activity
Biological process: negative regulation of cell population proliferation; negative regulation of epidermal growth factor receptor signaling pathway; negative regulation of interleukin-2-mediated signaling pathway; negative regulation of type I interferon-mediated signaling pathway; negative regulation of type II interferon-mediated signaling pathway; peptidyl-tyrosine dephosphorylation; regulation of hepatocyte growth factor receptor signaling pathway; B cell differentiation; erythrocyte differentiation; glucose homeostasis; insulin receptor signaling pathway; negative regulation of chemotaxis; negative regulation of ERK1 and ERK2 cascade; negative regulation of inflammatory response; negative regulation of insulin receptor signaling pathway; negative regulation of lipid storage; negative regulation of macrophage colony-stimulating factor signaling pathway; negative regulation of macrophage differentiation; negative regulation of platelet-derived growth factor receptor-beta signaling pathway; negative regulation of positive thymic T cell selection; negative regulation of receptor signaling pathway via JAK-STAT; negative regulation of T cell receptor signaling pathway; negative regulation of tumor necrosis factor-mediated signaling pathway; positive regulation of gluconeogenesis; regulation of type II interferon-mediated signaling pathway; and 2 more
Cellular component: cytosol; endoplasmic reticulum; endoplasmic reticulum-Golgi intermediate compartment; nucleoplasm; plasma membrane; cytoplasm; nucleus
Genetic constraint (gnomAD): Loss-of-function variants: 13 observed, 33.43 expected, observed/expected ratio (o/e) 0.39, 90% interval 0.25 to 0.62. The upper end of that interval is the gene's LOEUF score, 0.62, which puts it in group 2 of 6, group 1 being the genes least tolerant of losing a copy. Missense variants: 273 observed, 362.47 expected, observed/expected ratio (o/e) 0.75, 90% interval 0.68 to 0.83. Synonymous variants: 125 observed, 125.81 expected, observed/expected ratio (o/e) 0.99, 90% interval 0.86 to 1.15.
Homologues: Orthologues: macaque PTPN2 (99% identical), rabbit PTPN2 (95% identical), dog PTPN2 (93% identical), pig PTPN2 (91% identical), rat Ptpn2 (90% identical), mouse Ptpn2 (89% identical), guinea pig PTPN2 (80% identical), tropical clawed frog ptpn2 (67% identical), zebrafish ptpn2b (59% identical), zebrafish ptpn2a (56% identical), Drosophila melanogaster Ptp61F (41% identical). Paralogues in human: PTPN1 (56% identical), PTPRF (32% identical), PTPRD (30% identical), PTPRS (30% identical), PTPRT (30% identical), PTPRM (30% identical), PTPRA (29% identical), PTPRK (29% identical), PTPRC (28% identical), PTPRE (28% identical), PTPRG (27% identical), PTPRU (27% identical), and 23 more.
Diseases named in the same sentence as PTPN2 in open-access papers:
PTPN2 is named in the same sentence as 163 diseases in open-access papers, as found by Europe PMC text mining. Sharing a sentence is not in itself a finding about the gene and the disease. The quoted sentences say what the papers report.
type 1 diabetes (33 papers, 2010 to 2025). "A polymorphism in the PTPN2 rs2542151 GT or GG genotype is associated with an earlier onset of type 1 diabetes." (PMID 39682729, 2024). "PTPN2 is a known high-risk gene associated with type 1 diabetes, and polymorphisms are associated with the development of islet autoimmunity and the earlier onset of clinical diseases." (PMID 36497105, 2022). "While two non-coding risk alleles for PTPN2 have been associated with type 1 diabetes, we generated a functional knockout of the gene using CRISPR-Cas9 technology to probe for the effects of altered PTPN2 gene expression in human beta cells." (PMID 36497105, 2022). "PTPN2 inhibits pro-inflammatory pathways, including IFN-γ signaling, and mutations in PTPN2 are associated with chronic inflammatory and autoimmune diseases, including type I diabetes and Crohn’s disease." (PMID 35911672, 2022). "In type-1 diabetes, the PTPN2 mutation plays an important role in apoptosis of pancreatic beta cells but modulates intestinal epithelial barrier function and the innate immune response in CD." (PMID 30862129, 2019). "PTPN2 was associated with Crohn's disease and type I diabetes; ERAP1 was associated with psoriasis and multiple sclerosis." (PMID 25369137, 2014). "Genome-wide association screens identify PTPN2 as a susceptibility gene in the pathogenesis of type 1 diabetes whereas others report that TCPTP regulates cytokine-induced β-cell apoptosis." (PMID 24606867, 2014). "PTPN2 is associated with juvenile idiopathic arthritis, rheumatoid arthritis, celiac disease, type 1 diabetes and Graves' disease, providing an explanation for the increased incidence of several of these diseases in IBD patients." (PMID 22457781, 2012). "Genome-wide association studies have linked PTPN2 single nucleotide polymorphisms (SNPs) with the development of autoimmune diseases including inflammatory bowel disease, type 1 diabetes and rheumatoid arthritis." (PMID 22590589, 2012). "PTPN2 is particularly interesting as it has been implicated before in the pathogenesis of CD and type I diabetes." (PMID 21072187, 2010). "Examples include the association of IL23R variants with Crohn's disease (CD), psoriasis and ankylosing spondylitis, of PTPN2 variants with CD and type 1 diabetes, and of ORMDL3 variants with asthma and CD." (PMID 21072187, 2010). "PTPN2 mutations in human B cells are associated with earlier onset type 1 diabetes." (PMID 36497105, 2022). "PTPN2 is a known high-risk type 1 diabetes associated gene expressed in both immune- and pancreatic beta cells, but how genes affect the development of autoimmune diabetes is largely unknown." (PMID 36497105, 2022). "In addition, the type 1 diabetes-associated risk variant of PTPN2 rs1893217 independently contributed to diminished IL-2 receptor signaling in patient T-regulatory cells." (PMID 36497105, 2022). "Recent studies have reported that type 1 diabetes-associated PTPN2 intronic SNPs may result in decreased PTPN2 messenger RNA." (PMID 22590589, 2012). "The C allele of the SNP rs2542151 at PTPN2 gene, which we found to influence AS functional severity, was previously found to be associated with other autoimmune diseases, such as Crohn's disease, type 1 diabetes, and rheumatoid arthritis." (PMID 22984424, 2012). "PTPN2 has been implicated in the regulation of insulin signaling and glucose homeostasis and is also associated with chronic inflammatory and autoimmune diseases such as rheumatoid arthritis (RA), Crohn's disease, periodontitis, and type 1 diabetes mellitus (T1DM)." (PMID 30246029, 2018). "A further detailed analysis of protein levels using complementary assays convincingly demonstrates an upregulation of HLA class I molecules on the surface of PTPN2 KO sBC under steady state and upon proinflammatory cytokine exposure mimicking type 1 diabetes." (PMID 36497105, 2022).
type 1 diabetes (continued). "PTPN2 loss of function (LOF) results in systemic autoinflammation in mice, with high systemic cytokines and anti-nuclear antibody levels, supporting the association between PTPN2 LOF and several autoimmune conditions including type I diabetes, Crohn’s disease, and Celiac disease." (PMID 35911672, 2022). "Beta cell responses to viral infections are sensitized by the lack of Ptpn2 and results in increased apoptosis via Bim3 and demonstrates a direct interaction between type 1 diabetes risk genes and proapoptotic pathways in beta cells." (PMID 36497105, 2022). "Taken together, our results suggest that the dysregulation of PTPN2 expression in human beta cell may prime autoimmune T cell reactivity and thereby contribute to the development of type 1 diabetes." (PMID 36497105, 2022). "A non-HLA gene, PTPN2, known to affect the risk of type 1 diabetes and Crohn's disease was also identified in the mQTL analysis of human islets." (PMID 25375650, 2014). "Together with the mQTL findings in e.g. HLA genes and PTPN2, our results highlight that future studies may need to integrate genetics and epigenetics in order to clarify how candidate genes for type 1 diabetes contribute to the disease." (PMID 25375650, 2014). "Notably, it was found that mutations in autoimmune-related genes overlap between IBD and type 1 diabetes (T1D), such as protein tyrosine phosphatase non-receptor type 2 (PTPN2) and PTPN22, which negatively regulate T-cell activation and alter the composition of the gut microbiota in IBD patients." (PMID 39991152, 2025). "Loss of functional variants in the PTPN2 gene encoding T cell tyrosine phosphatase (TCPTP) is connected with an increasing risk of chronic inflammatory diseases, including rheumatoid arthritis and type I diabetes, Celiac disease and IBD, ulcerative colitis, and Crohn’s disease." (PMID 35154122, 2022). "Our results further indicate that activation of PTPN2 might be a very promising therapeutic approach for a broad range of chronic inflammatory and autoimmune disorders, including systemic lupus erythematosus, type-1-diabetes, rheumatoid arthritis, and psoriasis." (PMID 32973765, 2020).
autoimmune disease (30 papers, 2010 to 2025). A disorder resulting from loss of function or tissue destruction of an organ or multiple organs, arising from humoral or cellular immune responses of the individual to their own tissue constituents. "PTPN2 loss-of-function single-nucleotide polymorphisms are associated with autoimmune disorders in humans, and mice with global Ptpn2 deletion succumb to systemic immune activation a few weeks after birth." (PMID 37794185, 2023). "Loss-of-function (LOF) single-nucleotide polymorphisms in the PTPN2 locus are associated with several autoimmune diseases, which is probably due to the central role of PTPN2 in the regulation of inflammation." (PMID 37794185, 2023). "There are three autoimmune disease-associated variants in the PTPN2 gene shared across T1D, Crohn’s disease, and RA: rs2542151 in the coding region and rs1893217 and rs478582 both in the non-coding region." (PMID 35979360, 2022). "Genetic polymorphisms in the PTPN2 gene region have been linked with different autoimmune diseases such as T1D, rheumatoid arthritis, celiac disease and Crohn’s disease." (PMID 35526080, 2022). "PTPN2 is a negative regulator in the IL-2 signalling cascade and several SNPs in the PTPN2 gene region have been linked to different autoimmune diseases including T1D, rheumatoid arthritis and Crohn’s disease." (PMID 33193091, 2020). "Polymorphisms in the PTPN2 gene have been heavily linked with several autoimmune diseases including IBD." (PMID 33425916, 2020). "Genome-wide association studies (GWASs) raised particular interest in this molecule because loss-of-function single-nucleotide polymorphisms (SNP) in PTPN2 can confer a predisposition for the development of autoimmune diseases." (PMID 32726622, 2020). "PTPN2 is a key negative regulator of the immune and inflammatory responses, and its single nucleotide polymorphism is linked with a high susceptibility to autoimmune diseases." (PMID 29764444, 2018). "Here, we review how genetic variants shared across multiple autoimmune diseases have contributed to our understanding of global tolerance failure, focusing on variants in the human leukocyte antigen region, PTPN2 and PTPN22, and their role in antigen presentation and T and B cell homeostasis." (PMID 35979360, 2022). "This agrees with our findings, once deregulation of PTPN2 expression by the creation of a miRNA binding site by the risk allele could eventually reduce expression PTPN2, favoring autoimmune disease." (PMID 29755505, 2018). "The fact that the SNP rs2542151 in PTPN2 is associated with different aspects of autoimmune diseases suggests that these diseases, including AS, could share common pathogenic mechanisms." (PMID 22984424, 2012). "However, similar to STAT4, other IBD susceptibility genes such as IL23R, IL2/IL21, STAT3, and PTPN2 are associated with other autoimmune diseases." (PMID 20454450, 2010). "Numerous studies addressed the role of PTPN2 SNPs in several autoinflammatory/autoimmune diseases like inflammatory bowel disease (IBD), juvenile idiopathic arthritis, rheumatoid arthritis, and type I diabetes mellitus." (PMID 39320556, 2024). "PTPN2 has received considerable attention because reductions in its expression correlate with the development of autoimmune diseases." (PMID 32726622, 2020). "A further ubiquitously expressed phosphatase, PTPN2, has also been linked to RA and JIA, as well as other autoimmune diseases to be discussed in more detail later in this section." (PMID 33425916, 2020). "Genetic studies in autoimmune disease identified polymorphisms in IL-2 pathway genes encoding IL-2RA (CD25), IL-2, CTLA-4 and PTPN2 as key drivers in autoimmune disease susceptibility." (PMID 30446251, 2018). "PTPRM is a receptor-type protein tyrosine phosphatase, which is of particular interest as a number of protein tyrosine phosphatases have been linked to autoimmune disease, including PTPN22 and PTPN2." (PMID 20659327, 2010).
autoimmune disease (continued). "Additionally, key genes such as IL2RA and CD247, linked with risk genes PTPN22, PTPN2, and RUNX1, are consistently implicated across multiple conditions, including RA, lupus erythematosus, B-cell lymphomas, and autoimmune diseases." (PMID 40839671, 2025). "This work discovered genetic variations in KLRG1, CRTAM, SLAMF7, PTPN2, and KLRD1, which could be linked to altered PD-1-mediated cellular immune responses and may lead to autoimmune disorders." (PMID 38254179, 2024). "PTPN2 plays a regulatory role in many signaling pathways and biological processes, and activation of PTPN2 plays an important role in diseases such as atherosclerosis, tumors, inflammatory bowel diseases, autoimmune diseases, and diabetes." (PMID 37670950, 2023). "Controlled enhancement of PTPN2 function may be beneficial in autoimmune disease, while targeted inhibition of PTPN2 may help enhance the immune response to cancer." (PMID 35911672, 2022). "Moreover, PTPN2 is also expressed in tissues out with the hematopoietic system, and it is likely that its role in autoimmune disease is mediated through these as well." (PMID 33425916, 2020). "Thus, other factors in addition to IL2RA and PTPN2 genotype likely contribute to reduced response to IL-2 in these two autoimmune diseases." (PMID 24376757, 2013). "It is difficult to establish a definitive genotype-phenotype association, but it appears plausible that this proposed autoimmune critical region and PTPN2 on the short arm, as well as NFATc1 on the long arm may play a part in the autoimmune diseases seen in our patient." (PMID 29560252, 2017). "Additionally, genes involved in interleukin signaling pathways, including STAT3, TYK2, and JAK2, as well as PTPN2 (Tyrosine-protein phosphatase non-receptor type 2), which is associated with other autoimmune diseases, have been shown to contribute to the development of IBD." (PMID 40002718, 2025). "Interestingly, low KLRG1, PTPN2, and SLAMF7 levels have been observed in many autoimmune diseases, usually in the context of tissue-resident T cells." (PMID 38254179, 2024). "It is possible that in a subset of individuals, especially those prone to autoimmune disease, the administration of such PTP1B/PTPN2 inhibitors may result in immune-related toxicities, as also seen in patients receiving immune checkpoint therapies." (PMID 37500611, 2023). "Phosphatase tyrosine-protein phosphatase non-receptor type 2 (PTPN2) is a ubiquitously expressed negative regulator of the IL-2/IL-2R signalling cascade and has been investigated in different autoimmune diseases." (PMID 35526080, 2022). "However, there was no epistasis between PTPN2 and IL23R, although both genes predispose to autoimmune diseases." (PMID 22457781, 2012).